ZBED2 (zinc finger BED-type containing 2)
Description:
Transcriptional regulator which has intrinsic repressor activity and which competes with the transcriptional activator IRF1 for binding to the 5'-[CA]GAA[AC]C[CT]-3' consensus sequence in gene promoters. May thereby play a role in keratinocyte differentiation.
Synonyms: MGC10796
Tractability: PROTAC: ubiquitination databases record sites on it.
Gene: Protein-coding gene on chromosome 3 (111,592,900 to 111,595,346, reverse strand). Ensembl gene ENSG00000177494.
Subcellular location: Nucleus
Subcellular location (Human Protein Atlas): Cytosol; Mitochondria; Nuclear bodies
Gene Ontology:
Molecular function: DNA-binding transcription repressor activity, RNA polymerase II-specific; RNA polymerase II transcription regulatory region sequence-specific DNA binding; transcription cis-regulatory region binding; DNA-binding transcription factor activity, RNA polymerase II-specific; DNA binding
Biological process: negative regulation of transcription by RNA polymerase II; positive regulation of keratinocyte differentiation
Cellular component: nucleus; chromatin
Genetic constraint (gnomAD): Loss-of-function variants: 1 observed, 0.39 expected, observed/expected ratio (o/e) 2.55. That is too few expected variants to judge how well the gene tolerates losing a copy. Missense variants: 285 observed, 292.1 expected, observed/expected ratio (o/e) 0.98, 90% interval 0.88 to 1.08. Synonymous variants: 97 observed, 102.86 expected, observed/expected ratio (o/e) 0.94, 90% interval 0.8 to 1.12.
Homologues: Orthologues: chimpanzee ZBED2 (99% identical), macaque ZBED2 (96% identical), dog ZBED2 (90% identical), pig ZBED2 (86% identical), rabbit ZBED2 (83% identical).
Diseases named in the same sentence as ZBED2 in open-access papers:
ZBED2 is named in the same sentence as 6 diseases in open-access papers, as found by Europe PMC text mining. Sharing a sentence is not in itself a finding about the gene and the disease. The quoted sentences say what the papers report.
pancreatic cancer (3 papers, 2021 to 2024). "Notably, ZBED2 has recently been associated with basal identity in keratinocytes and regulation of inflammation in pancreatic cancer." (PMID 36944729, 2023). "Using ZBED2 ChIP-seq data from pancreatic cancer cell lines (the only ZBED2 ChIP-seq reported so far), we found a high confidence ZBED2 peak in the FOXA1 promoter (left)." (PMID 36944729, 2023). "Another study demonstrated that in pancreatic cancer, ZBED2 represses differentiation and dampens STAT2-mediated inflammatory response through IRES binding competition with IRF1." (PMID 36944729, 2023). "ZBED2 has previously been shown to promote pancreatic cancer cell invasion by inhibiting the IFN response." (PMID 34485257, 2021).
bladder cancer (1 paper, 2023). "In conclusion, both FOXA1 and ZBED2 inhibit inflammatory response and promote bladder cancer cell survival." (PMID 36944729, 2023). "Our findings and functional assays on FOXA1 and ZBED2 demonstrate that the enhancer set and TF networks identified herein represent prime targets for further pre-clinical investigation for bladder cancer treatment." (PMID 36944729, 2023). "We therefore sought to determine if ZBED2 is involved in the downregulation of interferon signaling in bladder cancer, potentially through interfering with FOXA1-activated pathways." (PMID 36944729, 2023). "Finally, our work also uncovers a role for both FOXA1 and ZBED2 in the regulation of inflammation in bladder cancer." (PMID 36944729, 2023). "Therefore, ZBED2 could directly dampen interferon response in bladder cancer, in agreement with its reported role in the pancreas." (PMID 36944729, 2023). "Our analysis revealed a network of TFs whose activity could be essential to Basal bladder cancer biology, including HMGA2, KLF7, NR3C1 and ZBED2." (PMID 36944729, 2023).
tumor (9 papers, 2018 to 2025). "To corroborate our findings, we interrogated RNA-seq from patients’ tissues and found that ZBED2 is the gene whose expression is more prominent in FGFR4 low tumours of the ICGC cohort." (PMID 35963908, 2022). "Therefore, given the dual role of FOXA1 and ZBED2 in the regulation of cell identity and inflammation, it will be important to study their link with tumour plasticity and in response to immunotherapy." (PMID 36944729, 2023). "ZBED2 had the highest coefficient value, suggesting that this gene may be related to tumor metastasis." (PMID 34485257, 2021). "Importantly, we also identified a Basal TF network, including ZBED2, KLF7, HMGA2, and NR3C1 as major regulators, whose expression was restricted to the basal component of tumours, according to scRNA-seq data." (PMID 36944729, 2023). "Notably, some genes related to exhaustion were also overexpressed in tumor‐infiltrating Tregs including TYMS, KIAA0101, CXCL13, CD27, HLA‐DQB1, HLA‐DMA, ENTPD1, CD200, DUSP4, and ZBED2." (PMID 32659053, 2020).
cancer (3 papers, 2020 to 2023). A tumor composed of atypical neoplastic, often pleomorphic cells that invade other tissues. "Our results indicate that high expression of ZBED2 is associated with metastasis of cancer and can be used as a diagnostic molecular marker." (PMID 34485257, 2021). "In parallel, we showed that both FOXA1 and ZBED2 play concordant roles in preventing inflammatory response in cancer cells through STAT2 inhibition." (PMID 36944729, 2023).
adenocarcinoma (1 paper, 2023). A common cancer characterized by the presence of malignant glandular cells. "In LUSC and adenocarcinoma, ZBED2 mainly regulates keratinization, which may be closely related to the pathological process of LUSC." (PMID 37575065, 2023).
ZBED2 also shares sentences with these, for which no sentence is quoted: melanoma (1 paper).